TRPV1 (transient receptor potential cation channel subfamily V member 1)
Diseases named in the same sentence as TRPV1 in open-access papers (continued):
Sharing a sentence is not in itself a finding about the gene and the disease.
Cerebral ischemia (continued). "On the other hand, more recent investigation demonstrates that post-ischemia TRPV1 inhibition limited neuronal damage by decreasing toll-like receptor 2 (TLR2) and TLR4, which are usually upregulated after brain ischemia and modulate inflammation and neuronal death." (PMID 37020858, 2023). "Therefore, DEX may reduce the entry of overload Ca2+ via modulation of TRPM2 and TRPV1 channel activations in the HIPPO and DRG neurons of rats with cerebral ischemia, and this effect should be clarified." (PMID 27872485, 2016).
colorectal cancer (14 papers, 2015 to 2025). A primary or metastatic malignant neoplasm that affects the colon or rectum. "Thus, the aim of the present study was to investigate the role of TRPV1 in colorectal cancer progression and provide a deeper understanding of the causal mechanisms of cancer cell proliferation and apoptosis." (PMID 31183372, 2019). "It is well known that TRPV1 activation in cancer cells such as urothelial, endometrial, and colorectal cancer cells, by strongly enhancing [Ca2+]i, promotes mitochondrial depolarization and ROS overproduction that leads to apoptotic cell death." (PMID 36876044, 2023). "For example, in skin carcinoma cells, pancreatic adenocarcinoma, or human colorectal carcinoma, TRPV1 suppresses posttranslational modification of the epidermal growth factor receptor (EGFR) associated with pro-proliferative pathways." (PMID 37507867, 2023). "TRPV1 activation by sulfide was demonstrated in primary cultures of colorectal cancer cells by ratiometric calcium imaging." (PMID 35745590, 2022). "Recently, studies have shown that inhibiting TRPV1 can increase the apoptosis sensitivity of colorectal cancer cells by regulating the ROS-JNK-CHOP pathway." (PMID 31183372, 2019). "In colorectal cancer, endocannabinoids and synthetic cannabinoids were able to induce apoptosis and inhibit carcinogenesis by mechanisms involving both CB receptors, TRPV1 channels and PPARγ-pathway." (PMID 26539529, 2015). "Another strategy that has been explored was the synergistic effect of silver nanoparticles (AgNPs) in enhancing the anticancer properties of 5-fluorouracil (5-FU), a chemotherapy drug commonly used in the treatment of colorectal cancer, which is characterised by TRPV1 expression." (PMID 40813985, 2025). "Moreover, another ECM protein, fibulin-5, was reported to induce apoptosis in colorectal cancer cells by downregulating TRPV1 expression." (PMID 34131404, 2021). "To investigate whether TRPV1 is dysregulated in colorectal cancer, we detected the endogenous level of TRPV1 in CRC tissues by using Immunohistochemical assay." (PMID 31183372, 2019). "However, the mechanism of TRPV1 inducing apoptosis of colorectal cancer cells remains to be further studied." (PMID 31183372, 2019). "Similarly, TRPV1 activation in colorectal cancer tissues leads to increased cytosolic Ca2+ concentration, which in turn reduces tumor growth and cell viability, highlighting TRPV1’s potential as a tumor suppressor in colorectal cancer through apoptosis induction." (PMID 39407657, 2024). "In colorectal cancer cell lines, cannabidiol reduced cell proliferation through antagonism of cannabinoid receptor type 1 (CB1) and transient receptor potential cation channel subfamily V member 1 (TRPV1), protected DNA from oxidative damage, and increased endocannabinoid levels." (PMID 31075907, 2019). "TRPV1 is a strong nonselective calcium channel that could powerfully affect the evolution of colorectal cancer cells, knowing from several studies that the imbalance of calcium influx is a stimulus for colon cancer development." (PMID 33379302, 2020). "Given that TRPV1 is a powerful nonselective Ca2+ channel, we hypothesize that TRPV1 can affect the growth of colorectal cancer cells by regulating Ca2+ dependent signaling." (PMID 31183372, 2019). "TRPV1 is a nonselective Ca2+ channel which has recently been observed in many cancers, while its effect on cell proliferation, apoptosis, metabolism, and cancer development in colorectal cancer (CRC) is still unclear." (PMID 31183372, 2019). "Since TRPV1 is a nonselective Ca2+ channel and intracellular Ca2+ homeostasis is critical for the survival and growth of colorectal cancer cells, we speculated that Ca2+-dependent effectors were involved in." (PMID 31183372, 2019).
gastroesophageal reflux disease (14 papers, 2008 to 2026). A chronic disorder characterized by reflux of the gastric and/or duodenal contents into the distal esophagus. "They discovered that menthol impeded the proliferation of esophageal epithelial cells, reduced TRPV1 expression in esophageal epithelial cells both in vivo and in vitro, and ameliorated pain and inflammation associated with reflux esophagitis." (PMID 39062591, 2024). "In particular, TRPV1 antagonists are currently used as therapeutic agents for heartburn and visceral hypersensitivity, but various TRP channels are likely to be proposed as targets for intestinal diseases." (PMID 35560982, 2022). "The TRPV1 channel is expressed in esophageal sensory neurons and afferent nerve fibers of different animal species, and mediates capsaicin-induced heartburn and esophageal sensitivity." (PMID 35562940, 2022). "Of note, TRPV1-positive cell density was strongly associated with chest pain and moderately associated with heartburn, which indicates the reduction of TRPV1 after radiofrequency ablation may at least play an essential role in relieving heartburn and chest pain in reflux hypersensitivity patients." (PMID 35386530, 2022). "TRPV1 can be activated not only by capsaicin but also by acid (and heat), making it a viable target to inhibit acid reflux-induced esophageal nociception." (PMID 34203134, 2021). "The effects of TRPV1 antagonist on heartburn and esophageal pain have been addressed by two clinical trials." (PMID 34203134, 2021). "A second aim was to explore TRPV1 gene transcription in relation to the mucosal barrier function and heartburn symptoms." (PMID 28534850, 2017). "It is known that TRPV1-immunoreactive sensory nerve fibers are expressed in human esophageal mucosa, and their expression increases in reflux esophagitis." (PMID 25215524, 2014). "The ability of TRPV1 to respond to low pH places it in a prime position to sense oesophageal acid reflux, giving rise to the sensation of heartburn, whilst intra-oesophageal capsaicin instillation induces symptoms of epigastric burning." (PMID 27713376, 2010). "The exposure of the oesophageal lining in patients with GORD to acid reflux and subsequent activation of TRPV1 may thus act as a catalyst for PAF release and trigger the inflammatory cascade." (PMID 36768825, 2023). "We hypothesized that NERD patients exhibit either an impaired mucosal barrier function and/or an upregulation of TRPV1 function that may account for heartburn symptoms." (PMID 28534850, 2017). "TRPV1 may contribute greatly to acid hypersensitivity in NERD, as TRPV1 activation by capsaicin infusion leads to heartburn." (PMID 28534850, 2017). "Berberine, the main active ingredient of Coptidis Rhizoma, and Evodiine (EVO), the main ingredient of Euodiae Fructus, are known to activate TAS2Rs and TRPV1 respectively and can be used in the treatment of gastroesophageal reflux disease (GERD)." (PMID 41501914, 2026). "In patients with gastroesophageal reflux disease (GERD), the density of TRPV1-immunoreactive sensory nerve fibers was increased in the inflamed esophagus." (PMID 34203134, 2021). "A second aim was to explore TRPV1 gene transcription in NERD patients in relation to the mucosal barrier function and daily heartburn symptoms." (PMID 28534850, 2017). "Building on the findings regarding the inhibitory impact of TRPM8 on TRPV1 in analogous research, it is anticipated that TRPM8 may emerge as a promising target for reflux esophagitis treatment." (PMID 39062591, 2024). "In patients with non-erosive reflux disease (NERD), total esophageal acid exposure time, but not heartburn symptom, was correlated with the density of immunoreactivity of TRPV1-positive fibers." (PMID 34203134, 2021). "Previous studies have shown an up-regulation of cytokines in gastroesophageal reflux disease and an increase of TRPV1-IR nerve fibers in similar diseases such as non-erosive reflux disease and inflamed human oesophagus." (PMID 18267041, 2008).
gastroesophageal reflux disease (continued). "It has been reported that activation of TRPV1 expressed in esophageal mucosa is involved in gastroesophageal reflux disease (GERD) or in nonerosive GERD symptoms." (PMID 26437435, 2015).
hepatocellular carcinoma (14 papers, 2010 to 2024). A malignant tumor that arises from hepatocytes. "Ca2+ influx mediated by TRPV1 activation is involved in human hepatoma HepG2 cell migration via a number of calcium-sensitive targets such as myosin light chain kinase, gel protein, non-actin, and calcineurin." (PMID 37569884, 2023). "Altogether, our data demonstrate that capsaicin activates AMPK in Hepatocellular carcinoma HepG2 cells by a mechanism involving TRPV1-calcium and CaMKKβ." (PMID 30695053, 2019). "Direct effects of hesperidin and capsaicin, individually and in combination, on mRNA of Trpv1 and Ucp2 were assessed in vitro in the human hepatoma-derived cell line HepG2." (PMID 30305645, 2018). "Taken together, these findings imply that a combination of TRPV1 and TRPV2 immunostains may separate low risk (TRPV1+/TRPV2−) and high-risk (TRPV1−/TRPV2+) hepatocellular carcinoma patients." (PMID 37240443, 2023). "Among members of transient receptor potential (TRP) channels activated in response to oxidative stress, we here identify that redox-sensitive TRPV1, TRPC1, TRPM2, and TRPM7 channels underlie Ca2+ entry and downstream cellular damages induced by APAP in human hepatoma (HepG2) cells." (PMID 26903865, 2016). "In particular, TRPV1 is upregulated in glioma, prostate, and pancreas cancers, whereas it is downregulated in hepatocellular carcinoma (HCC), bladder, and skin cancer." (PMID 30627539, 2018). "Thus, the action of APAP via the modification target cysteine residues may at least in part account for the important roles of TRPV1 or TRPC1 in APAP-induced responses in human hepatoma cells." (PMID 26903865, 2016). "In conclusion, this is the first study to systematically and comparatively analyze the contributions of redox-sensitive TRP channels such as TRPV1, TRPC1, TRPM2, and TRPM7 to human hepatoma cell death induced by APAP overdose." (PMID 26903865, 2016). "For instance, sorafenib is the standard systemic chemotherapy drug for the treatment of advanced hepatocellular carcinoma 124; capsaicin enhanced the antitumor sensitivity of sorafenib in hepatocellular carcinoma PLC/PRF/5 cells without obvious TRPV1 expression." (PMID 34131404, 2021).
neuroblastoma (14 papers, 2015 to 2025). Neuroblastoma (NB) is the most common solid, extracranial childhood tumor. "This work conducted experiment on temperature-activated transient receptor potential cation channel subfamily V member 1 (TRPV1) taken from mouse neuroblastoma and rat neuron cells, which are known to overexpress these ion channels." (PMID 33266097, 2020). "Comparing wildtype SH-SY5Y and TRPV1 transfected SH-SY5YhTRPV1 neuroblastoma cells, we showed dose-dependent capsaicin-induced increase in intracellular Ca2+ levels in TRPV1 transfected but not in wildtype cells." (PMID 31467355, 2019). "All‐trans‐retinoic acid (RA) induces to differentiate Trpv1‐expressing neuroblastoma cells into a neuronal phenotype." (PMID 30652078, 2019). "In terms of pheochromocytoma cells, an antagonist to GPR55 was able to counteract NADA-induced cell death, whereas cell death of neuroblastoma cells by NADA was mediated by TRPV1 activation." (PMID 31143113, 2019). "Transient transfection of TRPV1 into the F11 cell line, a hybridoma formed between dorsal root ganglion cells and neuroblastoma cells, were examined as an alternative to primary cell culture." (PMID 25569155, 2015). "To confirm the suitability of the differentiated neuroblastoma cell model for testing peptides that modulate TRPV1 and TRPA1 channel activity, we determined the levels of mRNA transcripts for TRPV1, TRPA1, and ASIC1a after 10 days of differentiation with RA + BDNF." (PMID 38203538, 2023). "Finally, this drug inhibited TPRV1 activation in TRPV1 transfected neuroblastoma cells, and prevented in vivo capsaicin-induced TRPV1 activation and resulting visceral hypersensitivity in normal rats." (PMID 31467355, 2019). "To screen at biochemical levels the principal pathways underlying TRPV1 degradation, we utilized the ND7/23 neuroblastoma cell line, a hybrid of mouse neuroblastoma and rat DRG neurons with endogenously expressed TRPV1." (PMID 39528731, 2025). "We found expression of ASIC1a, TRPV1, and TRPA1 channels in dopaminergic neuron-like cells derived from the neuroblastoma SH-SY5Y." (PMID 38203538, 2023). "AM404, a dual agonist of TRPV1 and Cannabinoid Receptor type 1, has been proven to prohibit the NFAT and NFκB pathways and to reduce migration and invasion of neuroblastoma cells." (PMID 37269788, 2023). "We investigated acid-sensing (ASIC) and transient receptor potential vanilloid-1 (TRPV1) and ankyrin-1 (TRPA1) ion channels present in untreated and differentiated neuroblastoma SH-SY5Y to propose a new means for their study in neuronal-like cells." (PMID 35205034, 2022). "Western blot was conducted to investigate the effect of zerumbone on the expression of α2A-adrenoceptor, TRPV1 and NMDA NR2B receptors in CCI-induced whole brain samples of mice as well as in LPS-induced SH-SY5Y neuroblastoma cells." (PMID 32194397, 2020). "Changes in the expression of α2A-adrenergic, TRPV1, and NMDA NR2B receptors in the LPS-induced SH-SY5Y neuroblastoma cells were analyzed 24 h after the administration of 8 μg/ml zerumbone, 16 μg/ml amitriptyline, and vehicle." (PMID 32194397, 2020). "We also did not detect any response to capsaicin (TRPV1 agonist) in pH-responsive RA-treated neuroblastoma cells." (PMID 35205034, 2022). "In the present research, we examined RA-treated human neuroblastoma SH-SY5Y in comparison with its untreated counterpart as a prospective in vitro model system to study native acid-sensing, transient receptor potential vanilloid-1 (TRPV1) and ankyrin-1 (TRPA1) ion channels." (PMID 35205034, 2022). "Therefore, untreated and RA-treated neuroblastoma SH-SY5Y cells are not a suitable model for the study of TRPV1 and TRPA1." (PMID 35205034, 2022). "In electrophysiological measurements, we did not observe any response to selective TRPV1 and TRPA1 agonists in RA-treated neuroblastoma cells." (PMID 35205034, 2022).
Alzheimer disease (13 papers, 2019 to 2026). A progressive, neurodegenerative disease characterized by loss of function and death of nerve cells in several areas of the brain leading to loss of cognitive function such as memory and language. "Moreover, TRPV1 has also been implicated in microglial autophagy, where its activation ameliorates Alzheimer disease-related learning and memory impairments." (PMID 41568154, 2026). "Another study using a mouse model of Alzheimer disease found that TRPV1 activation effectively attenuated cognitive and synaptic dysfunctions, especially improving spatial learning and memory." (PMID 41568154, 2026). "GSEA analysis showed significant enrichment of gene sets involved in Alzheimer’s disease, positive regulation of amyloid-β formation, leukocyte chemotaxis, unfolded protein stress and linoleic acid metabolism in microglia of TRPV1−/−/E4 (AAV-hTau) mice." (PMID 39468688, 2024). "More recently, capsaicin has been considered a potential therapeutic agent for Alzheimer’s disease (AD) by reducing cognitive impairment and regulating microglial autophagy via TRPV1." (PMID 37299434, 2023). "The complex role of TRPV1 in the modulation of neuronal structures might be involved in neurodegenerative pathologies such as Alzheimer’s disease." (PMID 33240883, 2020). "Indeed, a protective effect of TRPV1 in Alzheimer’s disease has been reported." (PMID 33240883, 2020). "Indeed, both effects of capsaicin were blocked by capsazepine and absent in Trpv1 knockout mice, thus implying that targeting TRPV1 may be useful for the treatment of Alzheimer's disease." (PMID 31263706, 2019). "Nucleus tractus solitarii (NTS) astrocytes regulate respiratory output through glutamatergic signaling, modulation of TRPV1 channels, contributing to respiratory control in OSA and Alzheimer's disease models." (PMID 41277876, 2025). "Thus, TRPV1-dependent hampering of AMPAR endocytosis might be a putative mechanism for TRPV1 positive modulation of RhoA, thus contributing to the development of Alzheimer’s disease." (PMID 33240883, 2020).